MAGT1 (magnesium transporter 1)
Description:
Accessory component of the STT3B-containing form of the N-oligosaccharyl transferase (OST) complex which catalyzes the transfer of a high mannose oligosaccharide from a lipid-linked oligosaccharide donor to an asparagine residue within an Asn-X-Ser/Thr consensus motif in nascent polypeptide chains. Involved in N-glycosylation of STT3B-dependent substrates. Specifically required for the glycosylation of a subset of acceptor sites that are near cysteine residues; in this function seems to act redundantly with TUSC3. In its oxidized form proposed to form transient mixed disulfides with a glycoprotein substrate to facilitate access of STT3B to the unmodified acceptor site. Also has oxidoreductase-independent functions in the STT3B-containing OST complex possibly involving substrate recognition. Could indirectly play a role in Mg(2+) transport in epithelial cells (Probable).
Synonyms: IAP; DKFZp564K142; OST3B; MRX95; SLC58A1; CDG1CC; PRO0756; XMEN; bA217H1.1
Tractability: Small molecule: a structure with a bound ligand is known. Antibody: UniProt places it where antibodies can reach, with high confidence; its Gene Ontology location is reachable by antibodies, with high confidence; UniProt predicts a signal peptide or a membrane-spanning region. PROTAC: ubiquitination databases record sites on it; its protein half-life has been measured.
Gene: Protein-coding gene on chromosome X (77,825,747 to 77,899,271, reverse strand). Ensembl gene ENSG00000102158.
Subcellular location: Cell membrane; Endoplasmic reticulum; Endoplasmic reticulum membrane
Pathways (Reactome):
Disease: Maturation of DENV proteins; Maturation of spike protein
Immune System: Neutrophil degranulation; PD-L1(CD274) glycosylation and translocation to plasma membrane
Metabolism of proteins: Asparagine N-linked glycosylation
Transport of small molecules: Miscellaneous transport and binding events
Gene Ontology:
Molecular function: magnesium ion transmembrane transporter activity
Biological process: cognition; magnesium ion transport; protein N-linked glycosylation; magnesium ion transmembrane transport; transmembrane transport
Cellular component: endoplasmic reticulum; endoplasmic reticulum membrane; membrane; oligosaccharyltransferase complex; oligosaccharyltransferase complex B; plasma membrane; azurophil granule membrane
Gene-disease validity (ClinGen):
ClinGen rates the evidence that MAGT1 causes each of these diseases.
X-linked immunodeficiency with magnesium defect, Epstein-Barr virus infection and neoplasia (X-linked): Definitive.
X-linked intellectual disability (X-linked): Disputed. An X-linked intellectual deficiency in which not enough information is known, reported or published to indicate whether a gene causes non-syndromic or syndromic presentations.
Homologues: Orthologues: chimpanzee MAGT1 (99% identical), macaque MAGT1 (99% identical), dog MAGT1 (97% identical), guinea pig MAGT1 (96% identical), rabbit MAGT1 (96% identical), pig MAGT1 (96% identical), rat Magt1 (94% identical), mouse Magt1 (94% identical), tropical clawed frog magt1 (82% identical), zebrafish magt1 (79% identical), Drosophila melanogaster Ostgamma (50% identical), Caenorhabditis elegans ZK686.3 (42% identical). Paralogues in human: TUSC3 (67% identical).
Diseases named in the same sentence as MAGT1 in open-access papers:
MAGT1 is named in the same sentence as 56 diseases in open-access papers, as found by Europe PMC text mining. Sharing a sentence is not in itself a finding about the gene and the disease. The quoted sentences say what the papers report.
Immunodeficiency (11 papers, 2020 to 2025). Failure of the immune system to protect the body adequately from infection, due to the absence or insufficiency of some component process or substance. "MAGT1 deficiency was initially recognized as a novel combined immunodeficiency because the affected patients showed defective development and function of T cells associated with chronic active EBV infections." (PMID 35145548, 2022). "CNNMs have been associated with a number of genetic diseases affecting ion flux and cancer development via their association with phosphatases of regenerating liver (PRL), whereas deficiencies in MagT1 have been linked to immunodeficiencies." (PMID 33513920, 2021). "One immunodeficiency affects cytosolic Mg2+ levels, required for PLCγ1 activation, via mutations in the magnesium transporter 1 (MAGT1) in patients with X-linked immunodeficiency with magnesium defect, EBV infection, and neoplasia (XMEN)." (PMID 32251475, 2020). "Yet, mutations in the MagT1 gene have been linked to N-glycosylation and immunodeficiency." (PMID 35819535, 2022). "Cognitive and language delay was also described in a child with immunodeficiency and a large MAGT1 gene deletion extending to the proximity of the ATRX promoter, a gene associated with ID." (PMID 32451662, 2020). "However, two other patients from unrelated families and an immunodeficiency phenotype had the same MAGT1 mutation but no ID." (PMID 32451662, 2020). "MAGT1 is now confirmed as a non-catalytic subunit of the oligosaccharyltransferase complex and facilitates Asparagine (N)-linked glycosylation of specific substrates, making XMEN a congenital disorder of glycosylation manifesting as a combined immune deficiency." (PMID 32451662, 2020).
primary immunodeficiency (9 papers, 2014 to 2025). "X-linked immunodeficiency with magnesium defect, Epstein-Barr virus infection, and neoplasia (XMEN) is a rare primary immunodeficiency caused by MAGT1 mutations." (PMID 41018333, 2025). "X-linked MAGT1 deficiency with increased susceptibility to EBV-infection and N-linked glycosylation defect (XMEN) disease is a primary immunodeficiency caused by loss-of-function variants in the MAGT1 gene." (PMID 35145548, 2022). "Loss of MAGT1 disrupts T cell signaling and leads to a novel human primary immunodeficiency and, furthermore, overexpression of MAGT1 is associated with development and metastasis of colorectal cancer." (PMID 34107880, 2021). "Furthermore, variants in the X-linked MAGT1 causing hypoglycosylation led to the re-classification of MAGT1 deficiency as a CDG, which was previously only associated with a primary immunodeficiency with a magnesium transport defect (XMEN)." (PMID 37858231, 2023). "We report a novel primary immunodeficiency, and a differential molecular diagnosis to CXCR4‐,DOCK8‐,GATA2‐,MAGT1‐,MCM4‐,STK4‐,RHOH‐,TMC6‐, and TMC8‐related diseases." (PMID 27896283, 2016).
lymphoma (6 papers, 2015 to 2025). A malignant (clonal) proliferation of B- lymphocytes or T- lymphocytes which involves the lymph nodes, bone marrow and/or extranodal sites. "Individuals with genetic deficiencies in MAGT1 exhibit a significantly increased predisposition to lymphoma." (PMID 41562087, 2025). "Mutations in the Magnesium transporter 1, MAGT1, also limit the T cell control of EBV-infected B cells leading to the X-linked disease, XMEN, predisposing patients to EBV-associated lymphomas." (PMID 39599857, 2024). "A recent study has shown that in patients with genetic deficiencies in the magnesium transporter MAGT1, who are particularly susceptible to EBV infection and EBV+ lymphomas, NKG2D plays an important role in the control of EBV infection by NK and CD8+ T cells." (PMID 26067064, 2015). "Therefore, similar to other related disorders associated with EBV infections (such as MAGT1 or ITK deficiency), the lymphoma incidence in STK4 deficient patients is assumed to be increased although the absolute number of reported cases, including the case presented here is still low (n = 3)." (PMID 30386345, 2018).
colon carcinoma (5 papers, 2017 to 2023). "Consistently, MagT1 is overexpressed in colon cancer and seems to be associated with tumor metastasis and anticancer drug resistance." (PMID 34067290, 2021). "We demonstrate that the different amounts of TRPM7 and MagT1 account for the different proliferation rate of sensitive and resistant colon carcinoma cells." (PMID 28094304, 2017). "Colon cancer LoVo cells show high levels of TRPM7 and low amounts of MagT1, while the opposite is true in their doxorubicin-resistant counterpart." (PMID 36984673, 2023). "Silencing TRPM7 in different cell types, among which colon carcinoma cells, thymocytes and human endothelial cells, does not influence intracellular Mg content, while knocking down MagT1 in mammalian cell lines lowered the levels of intracellular Mg33." (PMID 30385806, 2018).
glioma (5 papers, 2021 to 2023). A benign or malignant brain and spinal cord tumor that arises from glial cells (astrocytes, oligodendrocytes, ependymal cells). "Intriguingly, the overexpression of MAGT1 has been implicated in the occurrence and progression of glioma." (PMID 35416125, 2022). "With the aim to establish novel molecular mechanisms underlying glioma cell radioresistance, this study proposed a hypothesis that MAGT1 may regulate the ERK/MAPK signaling pathway and PD-L1 in glioma." (PMID 35416125, 2022). "MAGT1 is a mammalian Mg2+-selective transporter and has oncogenic functions in breast cancer, cervical cancer, and glioma." (PMID 37627167, 2023). "Our bioinformatics analysis identified differentially expressed MAGT1 in glioma, expression of which was subsequently determined in cohort data of TCGA database and microarray dataset as well as glioma cell lines." (PMID 35416125, 2022). "They used flow cytometry for apoptosis; western blotting for protein levels of hexokinase 2 (HK2), MAGT1, Bcl-2, and BCL2-associated X (Bax) in glioma samples; and CCK8 assay for cell viability." (PMID 35071748, 2022). "Following the in vitro experiments, we then moved to investigate the effect of MAGT1 on in vivo glioma formation in a mouse model established by stereotactic injection GL261 cells." (PMID 35416125, 2022). "In conclusion, MAGT1 enhances the growth and radioresistance of glioma cells through the ERK/MAPK signaling pathway-mediated upregulation of PD-L1 expression." (PMID 35416125, 2022). "We first determined the expression of ERK protein and found that glioma cells silencing MAGT1 presented reduced extent of p-ERK but almost unchanged level of total ERK protein)." (PMID 35416125, 2022). "It was noted that MAGT1 expression was highly expressed in glioma tissues of TCGA data and microarray dataset, which was then validated in glioma cell lines." (PMID 35416125, 2022). "Kaplan–Meier survival curves further revealed the positive correlation between MAGT1 expression and the poor prognosis of patients with glioma in TCGA-GBM and TCGA-LGG cohorts)." (PMID 35416125, 2022). "Next, the extent of p-ERK was revealed to be elevated in glioma cells in the presence of MAGT1 overexpression, and this elevation was abrogated when MAGT1 overexpression was combined with ERK inhibitor U0126)." (PMID 35416125, 2022). "Taken together, the data acquired in this study led to the conclusion that MAGT1 overexpression contributed to the growth and radioresistance of glioma cells through ERK/MAPK signaling pathway-mediated upregulation of PD-L1 expression." (PMID 35416125, 2022). "Mouse glioma cells with manipulated MAGT1 and ERK inhibitors were further injected into mice to assess the in vivo tumor formation ability of glioma cells." (PMID 35416125, 2022). "Ectopic expression of MAGT1 was revealed to promote the proliferation and radioresistance of glioma cells, which was attributed to the MAGT1-mediated activation of the ERK/MAPK signaling pathway." (PMID 35416125, 2022). "Collectively, our data suggested that MAGT1-mediated activation of the ERK/MAPK signaling pathway increased not only the cell proliferation but also the radioresistance in SHG-44 glioma cells." (PMID 35416125, 2022). "The expression pattern of MAGT1 in glioma tissues was first predicted by microarray profiling and then verified in glioma cells." (PMID 35416125, 2022). "Further to explore the downstream mechanisms, we unraveled that MAGT1 stimulated not only the cell proliferation but also the radioresistance in glioma cells by activating the ERK/MAPK signaling pathway." (PMID 35416125, 2022). "Collectively, our bioinformatics analysis revealed the overexpression of MAGT1 occurring in glioma tissues and correlated it with the poor prognosis in patients with glioma." (PMID 35416125, 2022).
glioma (continued). "Our findings corroborate previous studies where microRNA-199a-5p was revealed to repress glioma progression through impeding MAGT1 expression and the circ_0002755/miR-628-5p/MAGT1 axis was found to participate in the progression of glioma." (PMID 35416125, 2022). "Through Pearson’s correlation analysis, a positive correlation between MAGT1 expression and PD-L1 expression was identified in clinically collected tumor tissues from glioma patients)." (PMID 35416125, 2022). "According to the results, MAGT1 expression was obviously upregulated in the four glioma cell lines, as reflected by both Western blot) and qRT-PCR) assays." (PMID 35416125, 2022). "This study intends to explore the regulatory role of magnesium transporter 1 (MAGT1) in radiotherapy resistance of glioma through modulating ERK and programmed death-1-ligand 1 (PD-L1)." (PMID 35416125, 2022). "Our initial findings of the bioinformatics analysis identified MAGT1 as a candidate gene related to glioma due to its overexpression in glioma tissues, which was correlated with the poor prognosis of patients with glioma." (PMID 35416125, 2022). "Following the identification of the upregulated MAGT1 expression in glioma tissues and cells, we then explore the effect of MAGT1 on radioresistance of glioma cells." (PMID 35416125, 2022). "In summary, MAGT1 augmented the clonogenic potential of glioma cells and contributed to the resistance of glioma cells to irradiation." (PMID 35416125, 2022). "Further, colony formation ability of these cells was assessed under irradiation (2 Gy) to explore the effects of MAGT1 on glioma cell resistance to irradiation." (PMID 35416125, 2022). "As shown by flow cytometry, the apoptosis rate was obviously down-regulated by MAGT1 overexpression in both irradiated and unirradiated glioma cells, which could then be reversed by additional U0126-induced ERK inhibition)." (PMID 35416125, 2022). "They reported a three-way interaction between circ-0002755, mir628-5p, and MAGT1 and suggested that Sev could regulate the progression of glioma via the circ_0002755/miR-628-5p/MAGT1 axis." (PMID 35071748, 2022). "Additionally, MAGT1 overexpression accelerated the in vivo tumor formation of glioma cells, while the ERK inhibitor negated its effect." (PMID 35416125, 2022). "Taken together, MAGT1 may stimulate the viability of glioma cells via activation of the ERK/MAPK signaling pathway." (PMID 35416125, 2022). "Further, MAGT1 silencing resulted in suppressed viability of the cells and MAGT1 overexpression led to the opposite; meanwhile, the glioma cell viability-promoting property of MAGT1 overexpression was reversed by its combination with U0126-induced ERK inhibition." (PMID 35416125, 2022). "Also, by indicating the involvement of the MAGT1/ERK/MAPK axis in radioresistance of glioma cells, this study provides potential adjuvant therapies for enhancing the efficacy of radiotherapy in clinical treatment for glioma." (PMID 35416125, 2022). "Herein, our data substantiated the overexpression of MAGT1 in glioma cells." (PMID 35416125, 2022). "We then determined the PD-L1 protein level in glioma cells with manipulated MAGT1 expression." (PMID 35416125, 2022). "Afterward, we managed to validate the hypothesis that MAGT1 may affect the viability and radioresistance of glioma cells by regulating the ERK/MAPK signaling pathway." (PMID 35416125, 2022). "We then validated that MAGT1 was also overexpressed in glioma cells." (PMID 35416125, 2022). "Furthermore, our data substantiated that MAGT1 may trigger the proliferation of glioma cells and contribute to the resistance of glioma cells to irradiation." (PMID 35416125, 2022). "Artificial modulation of MAGT1, ERK, and PD-L1 expression was performed to examine their effects on glioma cell proliferation and radioresistance, as reflected by MTT and colony formation assays under irradiation." (PMID 35416125, 2022).
glioma (continued). "Among the four glioma cell lines, we selected for subsequent experiments the SHG-44 cell line, which presented with the highest MAGT1 expression." (PMID 35416125, 2022). "We then investigated the expression of MAGT1 in a normal human astrocyte (NHA) cell line and four glioma cell lines (SHG-44, A172, T98G and U251)." (PMID 35416125, 2022). "Taken together, MAGT1 enhanced PD-L1 expression by activating the ERK/MAPK pathway, thereby facilitating glioma cell growth." (PMID 35416125, 2022). "It was illuminated that MAGT1 stimulated PD-L1 expression through the ERK/MAPK pathway and thus facilitated glioma cell growth." (PMID 35416125, 2022). "In bioinformatics analysis, we took the intersection of upregulated genes identified in TCGA-GBM dataset, TCGA-LGG dataset, and the GSE140746 microarray, four glioma-related candidate genes were thereupon obtained, namely AQP4, BIRCS, MAGT1, and MGP)." (PMID 35416125, 2022). "In line with the prior documentation, our in vivo experiments substantiated that MAGT1 could enhance the expression of PD-L1 by activating the ERK signaling pathway, thereby contributing to the growth and radio-resistance of glioma cells." (PMID 35416125, 2022). "Altogether, our in vivo data, consistent with in vitro results, substantiated that MAGT1 could upregulate the expression of PD-L1 by activating the ERK signaling pathway, thereby stimulating the growth of glioma cells in vivo." (PMID 35416125, 2022). "Analysis on the TCGA-GBM and TCGA-LGG datasets unveiled the overexpression of MAGT1 in glioma tissues), and that on glioma-related GSE140746 microarray indicated higher expression of MAGT1 in glioma tissue after radiotherapy as compared with untreated glioma tissues)." (PMID 35416125, 2022). "In the present study, we elucidated that MAGT1 in glioma could activate the ERK/MAPK signaling pathway and upregulate PD-L1 expression, thereby contributing to the growth and radioresistance of glioma cells." (PMID 35416125, 2022). "Sev could also inhibit glioma cell proliferation and metastasis through the miRNA-124-3p/ROCK1 axis, KCNQ1OT1/miR-146b-5p/STC1 axis, miR-34a-5p/MMP-2 axis, and circ_0002755/miR-628-5p/MAGT1 axis." (PMID 35372041, 2022). "Furthermore, a previous report has pointed out that MAGT1 could activate the extracellular signal-regulated kinase (ERK) signaling pathway, which may consequently trigger the proliferation and invasion of glioma cells." (PMID 35416125, 2022).
breast carcinoma (4 papers, 2018 to 2026). "MAGT1 mutations were not statistically significantly associated with overall survival (OS) in breast cancer, but MAGT1 mutations were closely associated with ERBB2 and CDH1." (PMID 42006149, 2026). "In animal models, knocking out the magnesium ion transporter MagT1 significantly downregulated Ki67, thereby markedly inhibiting the progression of breast cancer." (PMID 39200180, 2024). "MAGT1 promotes key oncogenic phenotypes in breast cancer cells and may influence the immune landscape, highlighting its potential as both a prognostic biomarker and a promising therapeutic target." (PMID 42006149, 2026).
Epstein-Barr virus infection (4 papers, 2021 to 2025). An infection that is caused by Epstein-Barr virus. "We found one pathogenic variant in the NFKB1 gene in a father and his daughter, one pathogenic variant in the TNFRSF13B gene, and one pathogenic variant in the MAGT1 gene associated with X-linked immunodeficiency with magnesium defect, Epstein-Barr virus infection, and neoplasia (XMEN syndrome)." (PMID 38406025, 2024). "In the primary X-linked immunodeficiency with magnesium defect, the Epstein-Barr virus infection, and neoplasia (XMEN), magnesium transporter 1 (MAGT1) is mutated and the diminished intracellular magnesium levels compromise glycosylation and surface expression of NKG2D." (PMID 35053187, 2021).